PSMA1 (proteasome 20S subunit alpha 1)
Diseases named in the same sentence as PSMA1 in open-access papers (continued):
Sharing a sentence is not in itself a finding about the gene and the disease.
lung adenocarcinoma (2 papers, 2013 to 2020). A carcinoma that arises from the lung and is characterized by the presence of malignant glandular epithelial cells. "The dramatic results observed with PSMA1 knockdown are in contrast with those observed previously with bortezomib in vivo, including genetically engineered mouse models (GEMMs) of lung adenocarcinoma." (PMID 24040035, 2013).
ovarian carcinoma (2 papers, 2017 to 2020). A malignant neoplasm originating from the surface ovarian epithelium. "Next, we examined the prognostic significance of PSMAs in KM Plotter database, and the results showed that only PSMA1 was associated with PPS (HR = 0.83; 95% CI: 0.70–1.00; p = 0.044) for ovarian cancer patients." (PMID 27966459, 2017). "In ovarian cancer, only PSMA1 was marginally correlated with PPS." (PMID 27966459, 2017).
prostate tumors (2 papers, 2022 to 2024). "The efficacy of PSMA-1-MMAE-Pc413 in eradicating prostate tumors was assessed in male athymic nude mice inoculated with PC3pip tumors intravenously injected (i.v.)with different agents." (PMID 39000194, 2024). "The effectiveness of PSMA-1-MMAE-IR700 to eliminate prostate tumors was performed in mice bearing PC3pip tumors." (PMID 35265213, 2022).
colon adenocarcinoma (1 paper, 2018). "We first examined the differential expression levels of maspin, ANXA3, LAP3, and PSMA1 in normal colonic mucosa vs. colon adenocarcinoma by 1D Western blotting." (PMID 29423100, 2018).
COVID-19 (1 paper, 2024). A disease caused by infection with severe acute respiratory syndrome coronavirus 2. "Multiple proteasome subunits (e.g., PSMA1, PSMA5, PSMA6, PSMA7, and PSMB1) were upregulated in COVID-19 patients, especially during the acute phase of disease, potentially contributing to the dysregulation of proteasome activity." (PMID 38965561, 2024).
dysplasia (1 paper, 2022). A usually neoplastic transformation of the cell, associated with altered architectural tissue patterns. "Immunohistochemistry (IHC) staining showed that PSMA1 expression was relatively low in superficial gastritis (SG), upregulated in intestinal metaplasia (IM), moderately increased in dysplasia (DYS), and strikingly upregulated in GC tissues." (PMID 36424389, 2022).
Fever (1 paper, 2025). Body temperature elevated above the normal range. "Results showed that the levels of candidate proteins including HSP90α, VCAM1, PSMA1, and NID1 were higher in the fever stage of SFTS patients compared with healthy controls, almost reaching plateaus in the MOD stage, and the concentrations were decreased in the convalescent stage." (PMID 39973934, 2025).
kidney cancer (1 paper, 2017). Primary or metastatic malignant neoplasm involving the kidney. "In kidney cancer, Jones's dataset showed that the mRNA expression levels of PSMA1-4 were upregulated in renal pelvis urothelial carcinoma compared with normal kidney tissues." (PMID 27966459, 2017). "Consistent with the trend seen in Oncomine, the expression levels of PSMA1-4 and PSMA6-7 were significantly increased in 889 kidney cancers compared with 129 normal tissues in the TCGA mRNA HiSeq expression data." (PMID 27966459, 2017). "Notably, although PSMA1-4 and PSMA6-7 were increased in overall kidney cancer, the transcriptional patterns of PSMAs were different among the three subtypes." (PMID 27966459, 2017).
kidney chromophobe cell carcinoma (1 paper, 2017). "Compared with normal kidney tissue, PSMA1, PSMA3 and PSMA7 were upregulated in kidney chromophobe cell carcinoma, whereas PSMA5 was downregulated." (PMID 27966459, 2017).
leukemia (1 paper, 2013). A malignant (clonal) hematologic disorder, involving hematopoietic stem cells and characterized by the presence of primitive or atypical myeloid or lymphoid cells in the bone marrow and the blood. "These genes, including HNRNPL, EIF4H and PSMA1, were validated by qRT-PCR for use as control genes in leukemia." (PMID 24069164, 2013).
lymphoma (1 paper, 2015). A malignant (clonal) proliferation of B- lymphocytes or T- lymphocytes which involves the lymph nodes, bone marrow and/or extranodal sites. "Only seven genes (7%) were significantly (as determined by MuSiC analysis) mutated in both lymphoma immunophenotype groups, such as the proteasome subunit gene PSMA1, and the genes encoding the two uncharacterized proteins FAM90A1 and TBC1D26." (PMID 26377837, 2015). "Looking at the most significantly mutated genes in B-cell and T-cell lymphomas across the three studied breeds, genes not previously implicated in human lymphoma include well-known cancer-associated genes such as LTA4H and PSMA1, indicating potential treatment with proteasome inhibitors." (PMID 26377837, 2015). "In addition, a smaller fraction of the significantly mutated genes, such as PSMA1 and KPNA2, have not been reported in human lymphoma but have been reported in other human cancers." (PMID 26377837, 2015).
metastatic disease (1 paper, 2021). "To test the effectiveness of PSMA-1-VcMMAE against metastatic disease, we developed a metastatic prostate cancer model using intracardiac injection of GFP-expressing PC3pip cells, which are castration resistant." (PMID 33499427, 2021).
metastatic prostate carcinoma (1 paper, 2021). A carcinoma that arises from the prostate gland and has spread to other anatomic sites. "In in vivo studies, PSMA-1-VcMMAE significantly inhibited tumor growth leading to prolonged animal survival in different animal models, including metastatic prostate cancer models." (PMID 33499427, 2021).
non-small cell lung carcinoma (1 paper, 2017). A group of at least three distinct histological types of lung cancer, including non-small cell squamous cell carcinoma, adenocarcinoma, and large cell carcinoma. "The non-small cell lung cancer cell lines A549 and NCI-H460 treated with PSMA1 siRNA showed a loss of the chymotrypsin-like activity of proteasome and a significant decrease in homologous recombination-mediated repair of I-SceI-induced DNA double strand breaks." (PMID 27966459, 2017).
T-cell lymphomas (1 paper, 2015). "The most significantly mutated genes in Gr T-cell lymphomas are PSMA1, the cytochrome C oxidase subunit COX8A, and leukotriene A4 hydrolase (LTA4H)." (PMID 26377837, 2015). "Proteasome subunit gene PSMA1 is significantly mutated in both B- and T-cell lymphomas." (PMID 26377837, 2015). "LTA4H and PSMA1 have not been associated with human T-cell lymphoma, but have been associated with other human cancers and indicate new treatment options for Gr T-cell lymphoma." (PMID 26377837, 2015).
viral infections (1 paper, 2022). "From the ortholog analysis, we deduced that in order to explain the presence of the ERV observed in PSMA1, the viral infections must have occurred at the very least in the common ancestors of the subfamily Homininae." (PMID 36575684, 2022).
Wegener's granulomatosis (1 paper, 2013). "A detailed analysis of the fine specificity of antibodies against the different proteasomal subunits demonstrated antibodies against PSMA1 (also termed C2) in sera of patients with undifferentiated connective tissue disease and Wegener's granulomatosis." (PMID 23483977, 2013).
cancer (27 papers, 2012 to 2025). A tumor composed of atypical neoplastic, often pleomorphic cells that invade other tissues. "There are seven unique alpha subunits, PSMA1-7, of which several have been demonstrated to be closely associated with cancers." (PMID 27966459, 2017). "In addition to MCM2 to MCM7, six downstream oncogenic targets of c-MYC implicated in cancer survival and metabolism including PSMA1, PSMA6, PSMB2, HDAC2, LDHA and SPRING were positively correlated with IFITM3 in 71 GC specimens using the Cho dataset." (PMID 35941699, 2022). "We found that the migration, proliferation, and invasion of both PCa lines were reduced, suggesting that low expression of PSMA1 can effectively ameliorate the malignant phenotype of cancer cells." (PMID 40901472, 2025). "PSMA4, another proteasome, shares a similar fate as PSMA1, being that it is downregulated in cancer cells when those cells are treated with an anti-cancer compound." (PMID 38732562, 2024). "The proteasome subunit alpha type 1 (PSMA1) has been reported to act as an oncogene in several human cancers." (PMID 36424389, 2022). "To explore the clinical function of PSMA1 in human GC, we used RNA-seq from The Cancer Genome Atlas (TCGA) to analyze the mRNA expression of PSMA1 in GC." (PMID 36424389, 2022). "In this study, we systematically analyzed the mRNA expression levels of PSMA1-7 in multiple human cancers based on Oncomine and TCGA databases." (PMID 27966459, 2017). "Taken together, these results suggest that OTSSP167 suppressed mammosphere formation of cancer stem cells through the reduction of phosphorylated PSMA1 by inhibition of the MELK activity." (PMID 23283305, 2012). "We also investigated the biological characteristics of PSMA1 in cancer cells, and found that PSMA1 was stabilized by the phosphorylation in MELK overexpressing cells and that coexistence of PSMA1 and MELK enhanced the formation of mammosphere." (PMID 23283305, 2012). "The selective uptake of PSMA-1-Pc413 in these cancer tissues as well as the characterization and validation of PSMA expression on neovasculature in this syngeneic 4T1 model emphasizes their potential for advancements in targeted therapies and imaging techniques for BCa." (PMID 38760621, 2024). "It is speculated that PSMA-1-MMAE-IR700 + PDT may kill significantly more cancer cells than other treatment groups, leading to slower regrowth, i.e. less residual tumor cells, and/or therapeutic cures." (PMID 35265213, 2022). "Survival analysis also established a relationship with PSM gene expression and adverse clinical outcome, where PSMA1 and PSMD11 expression were linked to more unfavorable prognosis in ≥ 30% of cancer types for both overall survival (OS) and relapse-free interval (PFI)." (PMID 36123629, 2022). "In addition, PSMA-1-MMAE-IR700 was able to define the borders between the cancer tissue and normal tissue." (PMID 35265213, 2022). "Although the literature has separately confirmed the dysregulation of each gene of the PSMA family that was individually observed in various types of cancer, along with their involvement in other tumor-related issues, only PSMA1 and PSMA2 have so far appeared as potential candidates." (PMID 34943457, 2021). "For PSMA1, 7 of 8 patients showed overexpression in cancer (fourth row)." (PMID 29423100, 2018). "Hence, we investigated possible involvement of PSMA1 phosphorylation by MELK in the maintenance of cancer stem cell characteristics." (PMID 23283305, 2012). "In conclusion, the comprehensive pan-cancer analysis presented here demonstrated that several PSM genes (e.g. PSMA1, PSMB4-5, PSMB8-10, PSMD2, PSMD4, PSMD11, PSME1-3, and PSMG3) may be putative biomarkers for determining prognosis and choice of treatment for different cancer types." (PMID 36123629, 2022). "In the case of PSMA-1-MMAE-IR700, it can offer both adjuvant PDT and chemotherapy after FIGS to eradicate any unresected cancer cells, resulting in complete tumor removal." (PMID 35265213, 2022).
cancer (continued). "We propose that PSMA1 knockdown alone leads to increased protein levels of MDH2, thereby exerting cancer-promoting functions." (PMID 36527092, 2022). "For instance, seven PSM genes (i.e. PSMA1, PSMA4, PSMC1, PSMC3IP, PSMD13, PSMG2-3 (PSM class I/II/V)) were overexpressed in the majority of the 16 cancer types." (PMID 36123629, 2022). "The study identified genes in the ubiquitin proteasome system, including proteasome subunit alpha 1 (PSMA1) and proteasome subunit beta 2 (PSMB2), as essential genes in cancer cells." (PMID 35740614, 2022). "Fluorescence signal from PSMA-1-MMAE-IR700 was only observed in cancer tissues, but not in normal prostate or normal lymphocytes." (PMID 35265213, 2022). "More noteworthy, PSMA-1-MMAE-IR700 showed improved antitumor activity compared to co-administration of individual drugs (PSMA-1-IR700+MMAE with PDT), addressing the importance of simultaneous drug delivery to cancers." (PMID 35265213, 2022). "Thus, features such as EPB41, PSMA1, FGFR3, MRAS, and LEP which were involved in cancer-related pathways and with high PPI degrees (>/ = 10) were considered as PRBs for further analysis." (PMID 32528533, 2020). "Since the knockdown of PSMA1 expression suppressed the proliferation of cancer cells (data not shown), the PSMA1 is also considered to be essential for survival of cancer cells." (PMID 23283305, 2012). "Furthermore, by screening through the criteria of the PPI network, cancer-related pathway and TRS modeling, essential features with gene symbols of EPB41, PSMA1, FGFR3, MRAS, LEP, C7orf46, LOC285000, LBP, ZNF35, SLC30A3, LECT2, RNF7, and DYNC1I1 were identified as PRBs for COAD patients." (PMID 32528533, 2020).
tumor (27 papers, 1996 to 2025). "Single-cell sequencing revealed that tumor-associated neutrophils (TANs) exacerbate the tumor microenvironment (TME) by upregulating PSMA1, activating the NF-κB-HIF-1α axis, and promoting NET release, which drives malignant progression." (PMID 40901472, 2025). "Considering that tumor-associated neutrophils (TANs) may influence the tumor microenvironment by upregulating PSMA1 to induce hypoxia, we further focused on the role of PSMA1 in neutrophils." (PMID 40901472, 2025). "Tumor volumes in the PSMA1-deficient group were smaller than in the corresponding control group." (PMID 36424389, 2022). "Furthermore, tumor weights in the control group were heavier than that in the PSMA1-deficient group." (PMID 36424389, 2022). "Studies have shown that PSMA1 can regulate the NF-κB signaling pathway, increase oxidative stress, and thereby drive tumor progression." (PMID 40901472, 2025). "The group of PSMA-1-AuNPs + RT (6 Gy) mice showed a reduced rate of tumor growth and increased weight of mice." (PMID 39711799, 2024). "Although PSMA-1-Pc413 with PDT inhibited tumor growth and prolonged animal survival time, the survival benefit from the treatment was not significant as compared to the PBS group (p = 0.1905)." (PMID 39000194, 2024). "Successful accumulation of PSMA-1-AuNPs in the tumor was confirmed, with a peak at 4 h and elimination within 24 h." (PMID 39711799, 2024). "Fluorescence imaging of these animals showed positive tumor accumulation of PSMA-1-Pc413 in the primary tumors on the top right mammary fat pad of the animals as well as lung metastases (chest) and distant lower leg metastases." (PMID 38760621, 2024). "[211At]PSMA1 also showed a good treatment effect, but it showed relatively larger tumor size than [211At]PSMA5 did." (PMID 36344651, 2023). "[211At]PSMA1 also showed a substantial treatment effect; however, the tumor size was relatively larger compared to that with [211At]PSMA5." (PMID 36344651, 2023). "The result showed that [211At]PSMA5 exhibited the best tumor retention and excellent tumor growth suppression in LNCaP xenograft models compared to [211At]PSMA1." (PMID 36344651, 2023). "In the cellular uptake analysis, [211At]PSMA5 showed higher uptake than [211At]PSMA1, corresponding to the in vivo uptake in tumor xenograft models." (PMID 36344651, 2023). "Mice were irradiated by 50 J/cm2 of 690 nm light at the peak tumor accumulation of PSMA-1-MMAE-IR700, which was 1 h post injection." (PMID 35265213, 2022). "Western blot results of tumor tissues demonstrated that knockdown PSMA1 inhibited the expression of C-Myc, PCNA, Ki67, YAP, and TAZ, which was consistent with the results in vitro." (PMID 36424389, 2022). "Although we were not able to obtain the CDI values as the control mice started to die as early as on day 18, our data demonstrated that PSMA-1-MMAE-IR700 + PDT significantly inhibited tumor growth and extended animal survival as compared to the other 6 groups." (PMID 35265213, 2022). "The results showed that the expression level of PSMA1 in tumor tissues was upregulated compared to adjacent normal tissues." (PMID 36424389, 2022). "To validate the influence of PSMA1 on cell growth in vivo, we subcutaneously injected PSAM1-deficient AGS cells into the nude mouse and measured tumor volume every 3 days." (PMID 36424389, 2022). "In the group treated with 160 nmol/kg of PSMA-1-VcMMAE-Cy5.5, three out of five mice were tumor-free at end of the 90-day study and two mice had tumors grow back." (PMID 33499427, 2021). "In contrast, treatment with PSMA-1-VcMMAE showed the ability to inhibit tumor growth and prolong animal survival in a dose dependent manner." (PMID 33499427, 2021). "In contrast, administration of PSMA-1-VcMMAE-Cy5.5 effectively inhibited tumor growth as early as day 6 after the initial dose." (PMID 33499427, 2021).